KIF25 (kinesin family member 25)
Description:
Minus-end microtubule-dependent motor protein (By similarity). Acts as a negative regulator of centrosome separation required to prevent premature centrosome separation during interphase. Required to maintain a centered nucleus to ensure that the spindle is stably oriented at the onset of mitosis. May also act as a negative regulator of amino acid starvation-induced autophagy.
Synonyms: KNSL3
Tractability: No criterion of Open Targets' tractability assessment is met for any kind of drug.
Gene: Protein-coding gene on chromosome 6 (167,996,241 to 168,045,091, forward strand). Ensembl gene ENSG00000125337.
Subcellular location: Cytoplasm, cytoskeleton, microtubule organizing center, centrosome
Pathways (Reactome):
Hemostasis: Kinesins
Vesicle-mediated transport: COPI-dependent Golgi-to-ER retrograde traffic
Gene Ontology:
Molecular function: minus-end-directed microtubule motor activity; ATP binding; microtubule binding; microtubule motor activity
Biological process: establishment of spindle orientation; negative regulation of autophagy; negative regulation of mitotic centrosome separation; nucleus localization; mitotic sister chromatid segregation; organelle organization; protein homotetramerization; microtubule-based movement
Cellular component: centrosome; kinesin complex
Genetic constraint (gnomAD): Loss-of-function variants: 19 observed, 28.34 expected, observed/expected ratio (o/e) 0.67, 90% interval 0.47 to 0.98. The upper end of that interval is the gene's LOEUF score, 0.98, which puts it in group 4 of 6, group 1 being the genes least tolerant of losing a copy. Missense variants: 480 observed, 498.87 expected, observed/expected ratio (o/e) 0.96, 90% interval 0.89 to 1.04. Synonymous variants: 223 observed, 211.14 expected, observed/expected ratio (o/e) 1.06, 90% interval 0.95 to 1.18.
Homologues: Orthologues: macaque KIF25 (88% identical), chimpanzee KIF25 (79% identical), dog KIF25 (57% identical), zebrafish kif25 (48% identical). Paralogues in human: KIF1B (29% identical), KIF16B (29% identical), KIF1A (29% identical), KIF7 (29% identical), KIF1C (29% identical), KIFC2 (29% identical), KIFC3 (29% identical), KIF11 (29% identical), KIF13B (29% identical), KIF14 (29% identical), KIF18B (29% identical), KIF5A (29% identical), and 29 more.
Diseases named in the same sentence as KIF25 in open-access papers:
KIF25 is named in the same sentence as 12 diseases in open-access papers, as found by Europe PMC text mining. Sharing a sentence is not in itself a finding about the gene and the disease. The quoted sentences say what the papers report.
osteosarcoma (2 papers, 2022 to 2024). A usually aggressive malignant bone-forming mesenchymal neoplasm, predominantly affecting adolescents and young adults. "Inhibition of KIF25 can kill cervical cancer and osteosarcoma cells." (PMID 35874628, 2022).
endometriosis (1 paper, 2025). The growth of functional endometrial tissue in anatomic sites outside the uterine body. "In contrast, some genes were significantly downregulated in endometriosis patients, among others KIF22, KIF25, GAS2L2, and HINT3." (PMID 41516028, 2025). "Furthermore, the identification of upregulated genes, such as SIRT1, SBDS, SRF, SPN, P2RX1, TEAD3, and SLITRK3, alongside downregulated genes, including KIF22, KIF25, GAS2L2, and HINT3, highlights a broad transcriptional reprogramming within endometriosis-affected tissues." (PMID 41516028, 2025).
Kawasaki disease (1 paper, 2021). A rare inflammatory disease characterized by an acute febrile, systemic, self-limiting, medium-vessel vasculitis primarily affecting children. "The effect of five SNPs that showed to be the most statistically associated with the Kawasaki disease in this study was evaluated, this includes: rs12037447 in non-coding sequence and rs146732504 in KIF25, rs151078858 in PTPRJ, rs55723436 in SPECC1L, rs6094136 in RPN2 genes." (PMID 33692975, 2021). "We found that five single nucleotide polymorphisms were more commonly found in Polish children with Kawasaki disease than in adults: rs12037447 (non-coding region), rs146732504 (KIF25), rs151078858 (PTRPJ), rs55723436 (SPECC1L), rs6094136 (RNP2)." (PMID 33692975, 2021).
tumor (5 papers, 2023 to 2025). "LAP3, ADRA1D, KIF25, GPS2, and MCF2L genes were associated with proliferation, movement, and invasion of tumor cells." (PMID 39839768, 2024). "We chose 4 genes (KIF25, E2F1, DIP2C, TFG) that were present in at least 4 tumor patients, were not present in the healthy population, were detected outside of patients 18, 19, 30, 34, and 38, and have the potential to serve as therapeutic targets or diagnostic and predisposing biomarkers." (PMID 38982214, 2024).
cancer (3 papers, 2012 to 2023). A tumor composed of atypical neoplastic, often pleomorphic cells that invade other tissues. "These first clues to the KIF25 function in lysosomal trafficking and cancer biology warrant a closer study of this largely unknown member of the kinesin family." (PMID 23071517, 2012). "In this study, we identified KIF11, KIF20A, KIF21, KIF25, MYO1G, MYH1 and TPM2 as proteins whose depletion causes growth inhibition and non-apoptotic cell death in cancer cells." (PMID 23071517, 2012). "For the cancer phenotypes, the reverse genetics models were enriched in DNA repair functions (p = 2×10−5, FDR p = 0.03) (POLG/FANCI, SLX4/FANCP, XRCC1, BRCA1, FANCA, CHD1L) while the additive model showed enrichment related to chromatid segregation (p = 4×10−6, FDR p = 0.005) (KIF25, PINX1)." (PMID 24349080, 2013).
infection (1 paper, 2025). The state of being infected such as from the introduction of a foreign agent such as serum, vaccine, antigenic substance or organism. "In addition, Kif11, along with kinesins Kif18a and Kif25, were in proximity to L2 during infection." (PMID 39629998, 2025). "We repeated this PLA analysis with kinesins Kif18a and Kif25, since previously published data suggest that HPV requires these kinesins during infection." (PMID 39629998, 2025).
KIF25 also shares sentences with these, for which no sentence is quoted: breast carcinoma (1 paper); cervical cancer (1); colorectal adenoma (1); dementia (1); glioma (1); melanoma (1).